UPP1 (uridine phosphorylase 1)
Diseases named in the same sentence as UPP1 in open-access papers (continued):
Sharing a sentence is not in itself a finding about the gene and the disease.
tumor (continued). "This indicated that Upp1-expressing neutrophils from tumour-bearing mice strongly suppressed T-cell proliferation, whilst neutrophils isolated from Upp1−/− tumour-bearing mice had a reduced ability to suppress T-cell proliferation." (PMID 40702342, 2025). "In summary, these results suggest that CRISPRa upregulation of UPP1 in adipocytes and adipose organoids reduces uridine in the tumor microenvironment of PDA and leads to cancer growth suppression." (PMID 39905264, 2025). "Since both tumor and immune cells express UPP1, we conducted further analyses using single-cell RNA-Seq datasets to delineate the source of UPP1 expression in each cell type within the tumor microenvironment." (PMID 41243973, 2025). "Macrophage-released cytokines, including IL-1 and TNF-α, induce the expression of Upp1 in tumor cells." (PMID 41243973, 2025). "The upregulation of UPP1 in cancer cells has inspired studies focused on the tumour-intrinsic effects of UPP1." (PMID 40702342, 2025). "Overall, in most cancer types, the expression level of UPP1 is positively correlated with the estimated level of macrophage infiltration, as inferred by tumor deconvolution tools, including EPIC, TIMER, and CIBERSORT." (PMID 41243973, 2025). "This indicated that neutrophils from tumour-bearing mice had increased UPP1 activity, and consistent with the previous data, the increased uracil produced from UPP1-mediated cleavage of uridine was exported from the cell." (PMID 40702342, 2025). "UPP1-overexpressing tumor cells, UPP1-downregulated tumor cells, and their respective controls were subcutaneously implanted into both C57BL/6 mice and nude mice, respectively." (PMID 38331898, 2024). "Subsequent ELISA experiments confirmed that the secretion level of TGF-β1 from the tumor cells also significantly increased following UPP1 upregulation." (PMID 38331898, 2024). "Our cytokine array analysis reveals that the upregulation of UPP1 in tumor cells leads to the increased release of various immunosuppressive cytokines, with TGF-β1 being particularly prominent." (PMID 38331898, 2024). "These associations between UPP1high tumor cells and various immunosuppressive components in the TME highlighted the potential role of UPP1 in shaping an immunosuppressive microenvironment in LUAD." (PMID 38331898, 2024). "Our findings unveiled a significant upregulation in a variety of cytokines in UPP1-overexpressing tumor cells, including TGF-β1, GM-CSF, IL-1β, IL-6, IGFBP-3, CXCL5, CCL20, and VEGF, with TGF-β1 being the most prominently elevated." (PMID 38331898, 2024). "Functional experiments demonstrated that UPP1 promotes tumor cell proliferation and invasion and suppresses anti-tumor immune responses." (PMID 39380997, 2024). "This suggested that high UPP1 expression in tumor cells contributed to the upregulation of PD-L1 through the PI3K/AKT/mTOR pathway." (PMID 38331898, 2024). "Further cytometry by time-of-flight (CyTOF) analysis substantiates that upregulation of UPP1 in tumor cells contributes to the shaping of an immunosuppressive TME." (PMID 38331898, 2024). "Recent studies have confirmed that UPP1 liberates uridine-derived ribose to fuel tumor metabolism and thereby support cells proliferation." (PMID 38696320, 2024). "In contrast, the tumor weight and cell viability in the gemcitabine-treated UPP1-overexpressing group were significantly higher than those in the group treated with gemcitabine." (PMID 38385072, 2024). "To further investigate the impact of UPP1high tumor cells and their associated cell groups on the prognosis of LUAD patients, we constructed a UPP1-related TME module based on the marker genes of these five cell populations." (PMID 38331898, 2024). "The expression of UPP1 in tumor cells was then analyzed using the AI-based software, Aipathwell25,26." (PMID 38331898, 2024). "Specifically, CD4 + T cells, CD8 + T cells, THP-1-derived macrophages, and HFL1 fibroblasts were co-cultured with UPP1-overexpressing tumor cells." (PMID 38331898, 2024).
tumor (continued). "Subsequent flow cytometry analyses of the infiltrating CD8 + T cells in tumors observed that inhibiting UPP1 expression in tumor cells increased the proportion of tumor-infiltrating CD8 + T cells." (PMID 38331898, 2024). "Our observations from the co-culture of UPP1-overexpressing tumor cells with CD4 + T cells highlighted that UPP1 upregulation in tumor cells significantly drove the differentiation of CD4 + T cells into CD25 + FOXP3+Tregs." (PMID 38331898, 2024). "The results showed that tumor cells with high UPP1 expression were relatively more sensitive to both Bosutinib and Dasatinib." (PMID 38331898, 2024). "Recent research on UPP1’s role in LUAD have shown its capacity to modulate tumor cell sensitivity to glycolysis inhibitors, thereby driving glycolytic pathways and enhancing tumor growth." (PMID 38331898, 2024). "To substantiate that UPP1 upregulation in tumor cells can promote the shaping of an immunosuppressive microenvironment in vivo, we performed the CyTOF analysis, covering 21 TME-related protein markers." (PMID 38331898, 2024). "UPP1 was overexpressed in LLC-OVA tumor cells, consistently, the upregulation of UPP1 led to an increase in PD-L1 levels." (PMID 38331898, 2024). "This synergy between UPP1 inhibition and PD-L1 blockade underscored the significance of UPP1 as a modulator of the tumor immune microenvironment." (PMID 38331898, 2024). "Intriguingly, after suppressing UPP1 expression, there is an observed increase in tumor sensitivity to PD-L1 blockade in vivo." (PMID 38331898, 2024). "After integrating the identified 11 potential drugs with the drugs that UPP1 high tumor cells were relatively sensitive to, 3 potential drugs were selected, including Bosutinib, Dasatinib, and Erlotinib." (PMID 38331898, 2024). "In tumors with low glucose, UPP1 utilizes ribose from uridine to sustain tumor cell metabolism, enhancing their growth and survival." (PMID 38331898, 2024). "Using scRNA-seq datasets, bulk datasets, and CCLE mRNA and protein expression datasets, correlations between UPP1 and various tumor immune checkpoints were assessed." (PMID 38331898, 2024). "On the other hand, we compared the drug sensitivity differences between tumor cells with high and low UPP1 expression across the three datasets." (PMID 38331898, 2024). "Here, we approached from a different angle to explore the relationship between UPP1 and tumor immunity." (PMID 38331898, 2024). "Next, we conducted relative sensitivity experiments on these three drugs using tumor cells with overexpressed UPP1 and their control group cells." (PMID 38331898, 2024). "Subsequently, UPP1-overexpressing LLC-OVA tumor cells and control LLC-OVA cells were directly co-cultured with OT-1 CD8 + T cells and the results showed that UPP1-overexpressing tumor cells demonstrated a reduced susceptibility to T cell-mediated elimination." (PMID 38331898, 2024). "The tumor weight in the gemcitabine-treated UPP1 knockdown group was significantly lower than that in the group treated with gemcitabine." (PMID 38385072, 2024). "Lastly, scRNA-seq analyses of fibroblasts revealed that fibroblasts co-cultured with either UPP1-overexpressing tumor cells or control cells exhibited distinct gene expression profiles." (PMID 38331898, 2024). "In this study, an integrative approach that combined scRNA-seq with bulk data analysis in LUAD led to the identification of a specific tumor cell subpopulation characterized by elevated UPP1 expression." (PMID 38331898, 2024). "Using the high-throughput cytokine detection array, we observed that upregulation of UPP1 in tumor cells resulted in a significant rise in various cytokines." (PMID 38331898, 2024). "The results showed that the proportion of MMP11+ CAFs-like fibroblasts was significantly higher when co-cultured with UPP1-overexpressing tumor cells than with control cells." (PMID 38331898, 2024).
tumor (continued). "By blocking the release of TGF-β1 from UPP1-overexpressing tumor cells using TGF-β1 neutralizing antibodies, we observed a marked decrease in the LAG3 + PDCD1+ exhausted T cell population." (PMID 38331898, 2024). "Subsequently, our co-culture experiments revealed a pivotal role for TGF-β1 in the context of UPP1-overexpressing tumor cells." (PMID 38331898, 2024). "Fibroblasts in the presence of UPP1-overexpressing tumor cells displayed a higher CAF score and increased expression of CAF markers such as FAP and MMP11." (PMID 38331898, 2024). "Analysis of the AODs of paired and unpaired samples revealed that UPP1 expression in tumor tissues was higher than that in non-tumor tissues." (PMID 38385072, 2024). "To further assess the relevance of UPP1 in PDA tumours, we next analysed its expression in publicly available human PDA datasets." (PMID 37198494, 2023). "The marked anti-tumour effect of UPP1-KO prompted us to look for changes in the in vivo microenvironment." (PMID 37198494, 2023). "We also observed that UPP1-high tumours exhibit higher expression of glycolysis genes, indicating a potential link between the UPP1–uridine axis and energy metabolism." (PMID 37198494, 2023). "In both lines, contrary to the lack of a proliferative defect in vitro, we observed a markedly reduced tumour growth following UPP1-KO." (PMID 37198494, 2023). "Along these lines, we show that UPP1-KO in an orthotopic syngeneic model of PDA severely blunts tumour growth, thus the UPP1–uridine scavenging axis is important for PDA cells." (PMID 37198494, 2023). "We orthotopically implanted these two mouse lines and the corresponding UPP1-KO lines into the pancreas of syngeneic hosts and assessed tumour weight at end point." (PMID 37198494, 2023). "Metabolomic profiling of the orthotopic tumours revealed an increase in tumoural uridine and a drop in uracil in the UPP1-KO tumours as well as a profound change in the metabolome relative to vector controls." (PMID 37198494, 2023). "We found that the expression of UPP1 in tumor tissues was significantly correlated with tumor size, smoking status, TNM stage, lymph node metastasis, distant metastases, and recurrence." (PMID 36186123, 2022). "In LUAD, GSEA demonstrated that tumor glycolysis and apoptosis pathways in cancer are significantly enriched in response to UPP1 alteration in LUAD." (PMID 36186123, 2022). "The results showed that the expression of UPP1 is related to tumor glycolysis and the apoptosis pathway." (PMID 36186123, 2022). "Single-cell RNA transcription analysis was applied to compare the expression of UPP1 in tumor tissues and adjacent tissue." (PMID 36186123, 2022). "UPP1 Knockdown group (n=3) suppressed tumor growth and reduced tumor size compared to the control group (n=3)." (PMID 36186123, 2022). "Seven tumor antigens (ADA, FYN, HDC, NFKBIZ, RASSF4, SLC6A3, and UPP1) associated with inferior prognoses and higher-level infiltration of antigen-presenting cells in PRAD were identified, thus promising candidates for mRNA vaccine." (PMID 35547260, 2022). "In-depth analysis of the tumor revealed that UPP1 Knockdown induced apoptosis and decreased the expression of ENO1 and LDHA." (PMID 36186123, 2022). "In cultured LUAD cells and xenograft mouse models, UPP1 downregulation markedly suppresses tumor growth and inhibits glycolysis progression in LUAD." (PMID 36186123, 2022). "Among the differentially expressed transcripts, UPP1 was most significantly expressed in the tumor tissue." (PMID 36186123, 2022). "Consistently, RT-PCR analysis of UPP1 expression in paired LUAD tumor tissues (n=25) and adjacent normal tissues (n=25) revealed that UPP1 was upregulated." (PMID 36186123, 2022). "cg16270885, the probe that targets the CpG site of the UPP1 gene shows a decrease in methylation signal as tumor grade advances while the rest of the CpG sites were methylated as tumor grade progressed." (PMID 33498463, 2021).
tumor (continued). "They demonstrated that the higher the level of UPP1 in the tumor, the worse the prognosis and the shorter the survival time of cancer patients." (PMID 34906153, 2021). "Notably, we established a novel six‐gene (APOC1, GLTP, ISG20, SPP1, SLC24A3 and UPP1) prognostic signature and discovered for the first time that this signature was associated not only with intrinsic aggressive features but also with the tumour immune microenvironment." (PMID 34498424, 2021). "Several studies have explored the relationship between the expression level of UPP1 and prognosis in tumor patients." (PMID 32583596, 2020). "There is a significant difference in tumour size between higher UPP1 expression group and lower UPP1 expression group in TCGA." (PMID 31496029, 2019). "To validate the correlation of UPP1 expression with tumour size, we analysed by logistic regression." (PMID 31496029, 2019). "Patients with UPP1 higher expression had more advanced stage (TNM stage III/IV) tumours than the lower group." (PMID 31496029, 2019). "In gene expression studies of SRC transformed by several cells, the genes IL8/CEF4, VIP, HMOX1, PLCPI, and UPP1 were identified as signature SRC aggressive tumor genes." (PMID 28945796, 2017). "Coculture of BMDMs with tumor cells similarly upregulated Upp1 expression in tumor cells." (PMID 41243973, 2025). "Notably, this increase was substantially reduced when IL-1 or TNF-α receptors were genetically ablated, underscoring the essential roles of TNF-α and IL-1 in Upp1 upregulation in tumor cells cocultured with macrophages." (PMID 41243973, 2025). "In these instances, the authors used in vivo transplantation models to show that increased UPP1 expression could drive primary tumour growth." (PMID 40702342, 2025). "In line with the ex vivo data, Upp1 KO mitigated the tumor growth suppression induced by Cad KO." (PMID 41243973, 2025). "Metastatic primary tumours upregulate Upp1 in neutrophils, which elevates circulating uracil." (PMID 40702342, 2025). "Identifying UPP1 as a tumor growth and immune escape driver may be a promising therapeutic target for this devastating disease." (PMID 39380997, 2024). "In addition, we reveal that upregulation of UPP1 in tumor cells influences the release of immunosuppressive cytokines and the expression of PD-L1." (PMID 38331898, 2024). "The ability of UPP1-overexpressing tumor cells to resist T cell-mediated elimination, which can be partially reversed by PD-L1 blockade in vitro, further underscored the clinical relevance of the UPP1-PD-L1 axis." (PMID 38331898, 2024). "Interestingly, evidence also suggests that inhibiting UPP1 enhances the infiltration of anti-tumor T cells." (PMID 38331898, 2024). "Next, an experimental tumor lung metastasis model was established by injecting nude mice aged six weeks with shNC-transfected or shUPP1-transfected UM-UC-3 cells and Vector-transfected or UPP1-transfected T24 cells via the tail vein." (PMID 38385072, 2024). "We observed that both Bosutinib and Dasatinib could inhibit tumor growth in both the UPP1-overexpression and control groups." (PMID 38331898, 2024). "Notably, the degree of tumor growth inhibition was more prominent in the UPP1-overexpression group when treated with Bosutinib and Dasatinib." (PMID 38331898, 2024). "Furthermore, when UPP1-overexpressing tumor cells were co-cultured with macrophages, there was an evident upregulation of SPP1 expression in the macrophages." (PMID 38331898, 2024). "This phenomenon might be partly attributed to the changes in the tumor microenvironment following the alteration in UPP1 expression." (PMID 38331898, 2024). "In addition to the influence of TGF-β1, the upregulation of other cytokines in UPP1-overexpressing tumor cells hints at a broader role for UPP1 in modulating tumor immunity." (PMID 38331898, 2024).
tumor (continued). "While the treatment with TGF-β1 neutralizing antibodies could suppress the expression levels of FAP and MMP11 in fibroblasts when co-cultured with UPP1-overexpressing tumor." (PMID 38331898, 2024). "Similarly, inhibiting UPP1 expression on tumor cells significantly increased the ability of CD8 + T cells to eliminate tumors." (PMID 38331898, 2024). "Additionally, macrophages shifted towards an M2 phenotype, and fibroblasts exhibited pro-tumor characteristics in the presence of UPP1-overexpressing cells." (PMID 38331898, 2024). "On the other hand, when UPP1 expression in tumor cells was inhibited, although the downregulation of UPP1 led to a certain degree of tumor growth suppression in the nude mice, this inhibitory effect was significantly more pronounced in the immunocompetent C57BL/6 mice." (PMID 38331898, 2024). "These phenotype changes suggested that UPP1 may play a multifaceted role in tumor biology, not only influencing metabolic pathways but also modulating the TME and immune response." (PMID 38331898, 2024). "Similarly, the co-culturing of UPP1-overexpressing tumor cells with CD8 + T cells facilitated the transformation of CD8 + T cells towards a LAG3 + PDCD1+ exhausted T cell phenotype." (PMID 38331898, 2024). "Next, we focused on whether the upregulation of PD-L1 in UPP1-overexpressing tumor cells could affect the direct killing ability of CD8 + T cells." (PMID 38331898, 2024). "Thus, we specifically focused on the UPP1high tumor cell population and the role of UPP1 in the context of LUAD." (PMID 38331898, 2024). "Notably, in vivo studies revealed that UPP1 knockout (KO) tumors showed reduced vessel density and increased anti-tumor T cell (CD8 T cells) infiltration." (PMID 38331898, 2024). "In addition, the western blotting and flow cytometry analysis showed that the expression level of UPP1 positively related with PD-L1 in tumor cells." (PMID 38331898, 2024). "In contrast, the number of cells in the tumor derived from UPP1-transfected T24 cells was higher than that in the tumor derived from Vector-transfected T24 cells, and the pro-proliferative biomarkers were upregulated in the tumor derived from UPP1-transfected T24 cells." (PMID 38385072, 2024). "Finally, stratification of tumour datasets also showed that the high expression of UPP1 predicted poor overall survival outcome in three out of the four PDA patient cohorts we analysed." (PMID 37198494, 2023). "Furthermore, UPP1 promotes glycolytic metabolism and tumor growth and inhibits the antitumor effect induced by epigenetic regulation through histone acetylation." (PMID 36186123, 2022). "In our study, we observed that lactic acid production and glucose uptake were significantly decreased in response to UPP1 knockdown, and UPP1 knockdown increased the antitumor effect induced by 2-DG, suggesting that that UPP1 is capable of regulating tumor progression through the Warburg effect." (PMID 36186123, 2022). "Previous studies are consistent with ours in indicating that UPP1 might serve as an oncogene that regulates tumor progression by the regulation of glycolysis." (PMID 36186123, 2022). "Systemic uracil in UFT may compete for the activation of 5-FU in the tumor by UPP-1 and decrease anti-tumor activity." (PMID 26123924, 2015). "To determine whether tumour-intrinsic alterations in UPP1 were occurring during metastatic progression, and whether this was responsible for increased systemic uracil, we then compared the expression of Upp1 in clinical endpoint MMTV-PyMT tumours to normal mammary gland tissue from FVB/N mice." (PMID 40702342, 2025). "Indeed, whilst lung neutrophils from Upp1+/+ tumour-bearing mice oppose T-cell proliferation, a factor that contributes to immunosuppressed microenvironments, neutrophils from tumour-bearing Upp1−/− mice have a decreased ability to suppress the proliferation of cytotoxic CD8+ T cells." (PMID 40702342, 2025).